CXCR4 (C-X-C motif chemokine receptor 4)
Diseases named in the same sentence as CXCR4 in open-access papers (continued):
Sharing a sentence is not in itself a finding about the gene and the disease.
tumor (continued). "Unfortunately, in H69 xenograft (CXCR4 positive) bearing nude mice, 68Ga-AMD3100-ph-NODAGA showed lower accumulation of the radioactivity in the tumor than 64Cu-AMD3100, with comparable accumulation in immune-related organs." (PMID 37375261, 2023). "In CRC, CXCR4 is upregulated in chemoresistant tumor cells, and lymph node–derived stromal cells enhance resistance to oxaliplatin and 5‐FU via an SDF1/CXCR4 dependent manner." (PMID 37229486, 2023). "It possessed anti-tumor growth and metastasis inhibition effects through regulating the PI3K/AKT/mTOR and MMPs signaling pathways by reducing the expression of CXCR4 in triple-negative breast cancer (TNBC) cells." (PMID 37497001, 2023). "The aim of this study was to explore the chemopreventive activity of α-hederin with/without cisplatin; this was achieved by measuring the reduction in tumor masses and the downregulation in SDF1/CXCR4/pAKT signaling proteins and nuclear factor kappa B (NFκB)." (PMID 36986504, 2023). "In a model of liver metastasis, it was shown that the CXCR4 chemokine receptor on tumor cells and its ligand CXCL12 expressed by endothelial cells significantly promote tumor cell transendothelial migration." (PMID 37240247, 2023). "Activated RhoA and RhoC led to CXCR4-mediated migration of T-ALL cell lines to CXCL12, triggering leukemic tumor cells infiltration." (PMID 37497001, 2023). "For example, they could be used for imaging tumor cell invasion into host tissue followed by endoradiotherapy using the same target molecule, a strategy that has already been implemented clinically for the receptor CXCR4, with CXCR4-directed molecular imaging and radioligand therapy." (PMID 37444610, 2023). "In preclinical research on PDAC, inhibition of CXCR4 at both the pharmacological and genetic levels led to the rapid buildup of CD8+ T cells in tumors and a reduction in tumor growth." (PMID 37007004, 2023). "We tested the impact of inhibiting CXCR4 using AMD3100 with single-dose RT in orthotopic (intra-prostate and intra-osseous) PCa models in mice to reproduce the primary and metastatic tumor microenvironments more faithfully." (PMID 36831366, 2023). "Compared to CXCR4, which showed a smaller difference in SVs, CXCL12 displayed a significant difference in most splicing events in normal versus tumor tissues." (PMID 37198402, 2023). "In primary tumors, PCa-derived CXCL16 recruits CXCR6-expressing MSCs which upregulate PCa CXCR4 expression, induce EMT markers via CXCL12 secretion, and promote tumor growth in vivo in a subcutaneous model." (PMID 37025604, 2023). "Here, we found that BMI1, CD44, SOX2, OCT4, UBE2C, CXCR4 CSCs marker genes are significantly upregulated, while IGF1-R, KLF4, ALDH1A1, CD133, FAM3C are downregulated in the tumor core vs healthy mucosa of 24 patients with OSCC." (PMID 38096163, 2023). "In this study, we explored and found that highly expressed IFI6 in MSCs promoted the activation of the SDF-1/CXCR4 axis initiation in the TME, which served as a mediator in the stromal component–tumor cell interaction." (PMID 37670388, 2023). "Leptin induces tumor dissemination and metastasis of BCCs to bone tissue by activating the SDF-1/CXCR4 axis, and upregulation of CXCR4 contributes to bone metastasis and poor survival." (PMID 37686525, 2023). "While the VEGF/VEGFR axis is induced via autocrine mechanisms in ECs from only some patient samples (MF17, MF18, MF21), other cells in the tumor stroma secrete multiple factors that activate VEGF, BMP, PDGF, CXCR4, and apelin signaling in ECs of most samples." (PMID 37669110, 2023). "CXCR4 and CXCR3 were regarded to play important role on the homing and infiltration of T cells to the tumor sites, and were elevated on expanded PD-1+CD8+ T cells." (PMID 37377605, 2023). "Multiple investigations have demonstrated that CXCR4, TNF-α, and TGF-β play a role in regulating drug resistance in MSC located in the tumor environment." (PMID 36966336, 2023).
tumor (continued). "Nevertheless, when LECs express CXCR4 that later interacts with CXCL12 found on tumoral cells, tumor lymphangiogenesis and lymphatic metastasis are promoted." (PMID 37744339, 2023). "rP21 was observed to decrease the expression of CXCR4 and the MMP-9 gene, a marker of migration, selectively in tumor cells." (PMID 38188016, 2023). "68Ga-Pentixafor as radio ligand for CXCR4 has been proven an alternative to 18F- fluorodeoxyglucose (FDG) PET, showing clearly higher detection rates and a better tumour-to-background contrast." (PMID 37047331, 2023). "Previous research found that the proliferation and metastasis of BC are linked to several signalling pathways, and that specific cytokines in the tumour microenvironment (TME), such as CXCR4 and CXCL12, play an important role in BC metastasis." (PMID 37162544, 2023). "CCR5 antagonists (maraviroc, leronlimab) and CXCR4 antagonists (balixafortide, burixafor, GMI-1359, motixafortide) have also been shown to synergistically inhibit tumor development in combination with chemotherapy." (PMID 36173487, 2023). "Activation of the CXCL12/CXCR4 axis in the TME, thus, provides paracrine signaling that mediates integrin β1 clustering on the surface of tumor cells, promoting tumor EMT." (PMID 37371856, 2023). "These released factors by MSCs enhances the migration toward the tumor site in a CXCR4/SDF-1 dependent manner; in addition, the angiogenesis by VEGF increases the proliferation of tumor cells by forming new blood vessels." (PMID 38004925, 2023). "SHH pathway was demonstrated to be directly or indirectly involved in tumor angiogenesis, and activation of Hh signaling in CAF can upregulate the expression of CXCR4 and IGF1R in TME." (PMID 37784082, 2023). "The receptors known for CXCL12 are CXCR4 and CXCR7 and are expressed by tumor cells and a range of other cells, such as immune cells, fibroblasts, and endothelial cells." (PMID 38260135, 2023). "Mechanistically, MIF independently interacts with CD74 in a hetero-complex with CD44, CXCR2, CXCR4, and ACKR3 to initiate downstream MAPK and PI3K pathways, all of which influence tumor initiation, growth, and metastatic dissemination." (PMID 38065972, 2023). "In this study, we aimed to establish (for CXCR4) and evaluate (for FAP) a workflow demonstrating the utility and applicability of ML in the field of theranostics—by predicting ligand-related tumor microenvironments for other potential target structures." (PMID 36672341, 2023). "CXCL12 not only binds to CXCR4, but also to CXCR3 and DPP4 on tumor cells in our study, which is consistent with previous reports." (PMID 37719863, 2023). "CTNNB1 is a component of the Wnt signaling pathway, which regulates tumor growth and metastasis through the expression of ICAM-1, VCAM-1, CXCR4, and CCL18." (PMID 37190141, 2023). "In cancer cells, the HIF-1α is overexpressed, which regulates tumor survival-related genes, such as CXCL12 and CXCR4." (PMID 36207479, 2023). "The SDF1 receptor CXCR4 expressed by MSCs and the highly expressed SDF1 on the surface of tumor cells can migrate MSCs to the tumor through the CXCR4-SDF1 axis." (PMID 37666813, 2023). "At the same time, a CXCR4 antagonist (plerixafor, also known as AMD3100) induced tumor angiogenic inhibition-triggered necrosis (TAITN) in oral squamous cell carcinoma (OSCC)." (PMID 36671802, 2023). "In another study, M-E5 has a higher affinity for CXCR4 overexpressing human solid tumor cells and a stronger ability to inhibit CXCL12-induced tumor cell migration compared with E5." (PMID 36762192, 2023).
tumor (continued). "More importantly, STEAP4 and ADGRF5 specifically expressed in subgroup 3 and 4 showed a significant overexpression of CXCR4 and SRGN, which were closely related to tumor metastasis or immunosuppression in TME." (PMID 37221625, 2023). "CXCR4 was highly expressed in cluster 7 ECs, and this chemokine receptor binds to CXCL12-expressing TAMs and promotes tumor metastasis and progression, indicating the pro-cancer properties of this cell cluster." (PMID 37533434, 2023). "It has been reported that MMP-2 in tumor cells increases the expression of SDF1, leading to increased stem cell tropism toward tumor cells via the SDF1/CXCR4 axis." (PMID 36915092, 2023). "When blocking the respective GPCR receptor CXCR4, a greater number of macrophages and CD8+ T-cells infiltrate the tumor, reducing tumor growth and metastasis." (PMID 37834140, 2023). "For example, a CXCR4 antagonist Plerixafor (AMD3100), which can inhibit the secretion of VEGF-A from TAMs and lead to reduce tumor angiogenesis, has been used in clinical trials for treating solid tumors and children cancer." (PMID 36816959, 2023). "The interaction of the receptor CD184/CXCR4 with its ligand SDF-1(also called CXCL12), enhances the interaction of CSCs with the tumor microenvironment." (PMID 36864434, 2023). "Stromal cell–derived factor 1 (SDF1) can interplay with CXC motif chemokine receptor type 4 (CXCR4) and activate AKT and ERK1/2 signaling pathways, resulting in antiapoptotic effects and contributing to tumor cell survival in CLL cells." (PMID 37229486, 2023). "Olaparib also suppresses myeloid-derived suppressor cell migration via the SDF1α/CXCR4 axis and promotes the survival of CD8+ T-cells in tumor tissue." (PMID 37627063, 2023). "CXCR4 inhibition is therefore a potential strategy to enhance CAR T and NK cell infiltration into tumour sites." (PMID 35205725, 2022). "In particular, we discovered that macrophage migration inhibitory factor (MIF), which interacts with CD74+CXCR4+ and CD74+CD44+, was specifically expressed in tumor samples." (PMID 35967424, 2022). "We found that the high-risk group was significantly associated with higher expression level of immune checkpoints and immune inhibitory factors, including CCL2, CTLA4, CXCR4, IL6, LAG3, PDCD1, and TGFB1, indicating tumor immune evasion." (PMID 36092894, 2022). "In addition, our study revealed that MXRA8 expression correlated with the expression of multiple metastasis-associated chemokines (CXCL12, CXCL13, CCL9, CCL21, CXCR4, CXCR5, and CCR7), suggesting that MXRA8 may be involved in tumor invasion and metastasis by regulating the secretion of chemokines." (PMID 36703779, 2022). "Functionally, overexpression of CXCR4 induced EMT, stem-like behavior and motility of EOC cells in vitro and accelerated tumor xenograft growth in vivo." (PMID 35681259, 2022). "Pharmacological studies targeting CXCR4/CXCL12 axis demonstrated that CXCR4 antagonist releases T cells from CXCL12-rich stroma and increases T cell infiltration to tumor sites." (PMID 35265130, 2022). "It is thought that CXCR4 and CXCL-12 can be evaluated together in terms of the tumor microenvironment and used in microenvironment modeling in drug studies." (PMID 36551144, 2022). "High CXCL12 in the TME thus provides paracrine signaling via a feedback loop that mediates integrin b1 clustering at the tumor cell surface, promotes tumor EMT and prevents apoptosis via upregulated CXCR4 on tumor cells." (PMID 36244987, 2022). "For CXCR4-positive tumor burden, maximum SUV (SUVmax), tumor volume (TV), and fractional tumor activity (FTA, defined as SUVmean x TV), were calculated." (PMID 35312939, 2022). "The chemokine CXCL12 and its receptors CXCR4 and CXCR7 are involved in how tumor cells are released from the primary tumor and find their metastatic sites." (PMID 36358665, 2022). "Furthermore, the CXCR4 expression of tumour lesions could be confirmed by immunohistochemistry." (PMID 36140541, 2022).
tumor (continued). "Within 24 h of A. Paniculata exposure, they saw a substantial decrease in mRNA expression of TM4SF3 and MMP9 in a concentration-dependent manner, inhibition of expression of HER2, CXCR4, MMP2, and MMP9, and depreciating tumor nodules." (PMID 35682652, 2022). "Specific to MIF signaling in tumor tissue, CellChat identified ligand MIF and its multi-subunit receptor CD74+CXCR4 as the most significant signaling, contributing to the communication from CD4+ T cells to CD8+ T2 and CD8+ T3 cells." (PMID 35812372, 2022). "The key ligands involved in MSC homing include chemokine receptors CCR2, CXCL12, and CXCR4 and adhesion ligands, such as SELPLG and SELP, among which CXCR4 is one of the most important molecules mediating the tumor-homing effects of MSCs." (PMID 35463812, 2022). "A role of CXCR4 in antitumor responses is unexpected, since the CXCL12-CXCR4 axis has been generally correlated with tumor cell growth, survival, invasion and metastization." (PMID 35565443, 2022). "The tumour volumes in the BsNb PX4 group were smaller than those in the atezolizumab group or the combination treatment group, including Nb PD-L1 and Nb CXCR4." (PMID 36284271, 2022). "Genetically engineered NK cells with both tumour-specific chimeric antigen receptor (CAR) and induced CXCR4 chemokine expression can improve immunotherapy in solid tumours, partially by increasing tumour infiltration of NK cells." (PMID 35806034, 2022). "The CXCL12/CXCR4 axis can transactivate HER2 and promote intraosseous tumor growth in prostate cancer." (PMID 36254250, 2022). "Beside the evaluation of the absolute tumor as well as TIC expression in primary and recurrent cancer biopsies the corresponding ratios for pCXCR4 and CXCR4 were generated and analyzed." (PMID 35397601, 2022). "A tissue microarray (TMA) of 37 tumor specimens of primary DTC was analyzed by immunohistochemistry (IHC) for the expression of CD8+, CXCR4, phosphorylated CXCR4 and SDF-1." (PMID 36419107, 2022). "It was consistent that the expression levels of PGK1, CXCR4, p-AKT, p-ERK in xenograft tumor tissues were increased in 786-O-PGK1 group compared with the 786-O-NC group." (PMID 35121728, 2022). "Labelled MSCs maintained tumour tropism and the IONPs in the LDGI complex were found to upregulate CXCR4 on the MSCs." (PMID 35103937, 2022). "The CXCL12 chemokine mediated pro-angiogenic and prometastatic effects through receptors CXCR4 and CXCR7, while the neutralization of this chemokine reduced the angiogenic potential of the tumor." (PMID 36354566, 2022). "The present experiments were performed with the human tumor cell lines, A549, DLD-1, and MDA-MB- 231, which we previously characterized for expression as well as their use of CXCR4, CXCR3, and CXCR7 in CXCL12- and CXCL11-dependent chemotaxis." (PMID 36539774, 2022). "CXCR4 can direct the migration of CD8 T cells and NK cells to tumor sites but can also impede the infiltration of T cells to tumor cells through CXCL12." (PMID 35265130, 2022). "The gradient established between CXCR‐4 expressed on tumour cells and CXCL12 produced by stromal and lymphatic endothelial cells enhances tumour cell metastasis." (PMID 36398426, 2022). "In turn, CXCL12 presentation in the TME and its resulting concentration gradients attract circulating CXCR4/CXCR7+ EPCs and promote tumor re-vascularization." (PMID 36568151, 2022). "HSCs were activated by tumor-derived CXCR4 and differentiated into CAFs via the SDF-1-CXCR4-TGF-β pathway to promote liver metastasis." (PMID 36348319, 2022).
tumor (continued). "CXCL12 and CXCR4 within the TME generally promote tumor angiogenesis and the survival and proliferation of tumor cells; they also recruit immune cells and direct them to specific immunosuppressive responses." (PMID 35565443, 2022). "CXCR4 antagonists can block CXCL12-dependent growth and proliferation signals, inhibit tumor cell metastasis and angiogenesis, and reduce drug resistance in tumor cells." (PMID 35893797, 2022). "The CXCR4/CXCL12 (SDF-1) axis enhances metastasis by mediating the migration and proliferation of tumor cells and inducing angiogenesis via the Akt signaling pathway." (PMID 36499667, 2022). "PGE2 is involved in inflammation, angiogenesis, tumor progression via MDSCs recruitment, ARG1 upregulation and regulation of PD-L1 expression on tumor-infiltrating MDSCs, promotion of CXCL12/CXCR4-mediated recruitment of MDSCs." (PMID 35158779, 2022). "In parallel, glucomannan can also inhibit the expression of major chemokine receptors, chemokine receptor 4 (CXCR4) and CC chemokine receptor 7 (CCR7), found in a wide range of tumor cells, thus reducing the dissemination ability of tumor cells." (PMID 36360194, 2022). "C25 actively secretes FGF7 and CTGF, which promote CAF growth and tumor angiogenesis, and CXCL12, which interacts with CXCR4 to block and deplete the T-cell response." (PMID 35664733, 2022). "Tumor PCs also increased CX43 expression in MSCs, and led to an elevated CXCL12 expression and stimulated CXCR4 expressed on MM cells." (PMID 35958625, 2022). "The authors attributed this difference to the dynamic nature of the CXCR4, which is expressed mainly in the TME compared to PSMA and SSTR, which are more stable and expressed in the tumour cell surface." (PMID 36140541, 2022). "(A–D) The treated (right side) and untreated tumors (left side) were harvested at the end of the experiment and analyzed for the CD8+/CD4+ ratio (A) and the frequency of CD8+ (B), CD8+ CXCR4+ (C), and CD8+ CXCR3+ (D) in the tumor microenvironment (TME)." (PMID 35314027, 2022). "CXCR4 is a specific receptor of SDF-1α, which is involved in tumor growth, invasion, and metastasis." (PMID 36159583, 2022). "CXCR4 is overexpressed in 88.33% (65/78) of HCC, where it plays a significant role in the metastasis of HCC by promoting the migration of tumour cells." (PMID 36140541, 2022). "In OS6, C25 actively secreted FGF7 and CTGF, which promoted CAF growth and tumor angiogenesis, and CXCL12, which interacted with CXCR4 to block and deplete the T-cell response." (PMID 35664733, 2022). "After transfection of tumor-derived DNA, the expression of CXCL12-CXCR4 axis, P-ERK1/2, and MMP2/9 proteins was further significantly increased under CXCR4 overexpression." (PMID 35860597, 2022). "The blockade of CXCR4, by an FDA-approved agent AMD3100, inhibited Ly6G+ neutrophil infiltration into the tumor and improved the efficacy of anti-VEGF therapy." (PMID 35158807, 2022). "C-X-C motif chemokine receptor 4 (CXCR4) is highly expressed in more than 20 different types of tumors and plays an important role in tumor development, invasion, and metastasis, as well as cell-microenvironment interaction." (PMID 35050416, 2022). "CXCR4-oe and CCR7-OE enhance the stimulation of erK1/2/MMP2/9 signaling pathway by tumor-derived DNA in HCC cells." (PMID 35860597, 2022). "The functions of CXCR4/CXCL12 extend beyond cell migration and involve the recognition and disposal of unhealthy or tumor cells." (PMID 35565443, 2022). "CXCR4 is a specific receptor of chemokine stromal cell derived factor (SDF-1α), which is involved in tumor growth, invasion, and metastasis." (PMID 36131788, 2022). "ECs in the tumor microenvironment overexpress CXCR4 in response to hypoxia and the secretion of CXCL12 by tumor cells and cells in the tumor microenvironment, recruits ECs into the tumor." (PMID 35155581, 2022).